AQP4 (aquaporin 4)
Diseases named in the same sentence as AQP4 in open-access papers (continued):
Sharing a sentence is not in itself a finding about the gene and the disease.
pneumococcal infection (1 paper, 2022). Infections with bacteria of the species streptococcus pneumoniae. "It is evident that during the course of pneumococcal infection, the progressive retraction of the astrocytic cellular processes causes the displacement of the AQP4, which loses its natural localization connecting the astrocytic end feet with the BBB vascular endothelium." (PMID 36036510, 2022). "On the other hand, Pavan and collaborators have recently observed that upon neuroinflammation caused by a pneumococcal infection in the CNS, AQP4 expression levels are not significantly altered compared to those in a noninfected situation." (PMID 36036510, 2022).
Polydipsia (1 paper, 2019). Excessive thirst manifested by excessive fluid intake. "The primary polydipsia associated with the inhibition of ACE declined inner medullary aquaporin (AQP) 2, without significant change AQP3 and AQP4 expression." (PMID 31116771, 2019).
portal hypertension (1 paper, 2025). Increased blood pressure in the portal venous system. "In hepatic encephalopathy models, portal hypertension triggers systemic inflammation and cerebrovascular endothelial dysfunction, suppressing AQP4 polarization in astrocytic endfeet and disrupting glymphatic flow." (PMID 41174538, 2025).
psoriatic arthritis (1 paper, 2025). Joint inflammation associated with psoriasis. "All 3 patients with AQP4-IgG seronegative NMOSD had a concurrent diagnosis of SLE while the 3 patients diagnosed with MOGAD had SLE, psoriatic arthritis, and UCTD, respectively." (PMID 39442039, 2025).
pulmonary edema (1 paper, 2018). Accumulation of fluid in the lung tissues causing disturbance of the gas exchange that may lead to respiratory failure. "To investigate whether PCS enhanced alveolar cell hyperpermeability during pulmonary edema in human disease of CKD-ULI, we additionally investigated the effect of PCS on the expression of aquaporin-4 in our cell model." (PMID 30205620, 2018).
pulmonary TB (1 paper, 2014). "We report a rapidly progressive and fatal case of anti-Aqp-4 antibody-positive neuromyelitis optica (NMO) like disorder in a patient receiving treatment for pulmonary TB." (PMID 25169022, 2014). "We report a fatal case of anti-aquaporin-4 antibody positive NMO spectrum disorder in a patient who was receiving treatment for pulmonary tuberculosis." (PMID 25169022, 2014).
relapsing (1 paper, 2022). "When comparing MOG and AQP4-associated NMO spectrum disorders, it has been found that NMO patients with MOG antibodies tended to have a single attack and/or fewer attacks than NMO patients with AQP4 antibodies who experienced significantly higher rates of relapsing disease." (PMID 35399911, 2022).
Respiratory insufficiency (1 paper, 2016). "Respiratory insufficiency due to brainstem inflammation has previously been identified as the main cause of death in AQP4-IgG-positive NMO." (PMID 27802825, 2016).
rotator cuff tear (1 paper, 2020). "To investigate a novel mechanism underlying skeletal muscle atrophy, we examined AQP4 expression and its regulation in muscle using the rotator cuff tear (RCT) model." (PMID 32843684, 2020).
sarcoglycanopathies (1 paper, 2023). "AQP4 expression was also assessed in patient muscle biopsies affected by sarcoglycanopathies, namely LGMD 2C-F caused by deficiencies of α, β, γ, and δ-sarcoglycan." (PMID 36675000, 2023). "In conclusion, AQP4 reduction in sarcoglycanopathies is associated with a corresponding decrease in α-syntrophin." (PMID 36675000, 2023).
Schistosomiasis japonica (1 paper, 2015). Schistosomiasis caused by Schistosoma japonicum. "Our results showed an enhanced granulomatous response with increased accumulation of eosinophils and macrophages around eggs in the liver of AQP4 KO mice with Schistosomiasis japonica." (PMID 25604731, 2015). "In addition, our study demonstrated enhanced Th2 but reduced Th1 and Treg cells generation in AQP4 KO mice with Schistosomiasis japonica, which may, at least partly, account for the enhancement of the liver granuloma formation." (PMID 25604731, 2015).
spinal cord syndrome (1 paper, 2015). "All three patients, aged 79, 82 and 88 years, presented with a spinal cord syndrome as the first clinical manifestation of AQP4-Ab-positive NMOSD." (PMID 25957640, 2015).
subependymoma (1 paper, 2015). Subependymoma is a rare and slow growing type of ependymoma, often presenting in middle-aged adults, found more commonly in men than in women, usually located in the fourth and lateral ventricles and manifesting with variable symptoms including headache, nausea, and loss of balance. "Using immunohistochemistry, we observed different aquaporin expression patterns depending on localization: aquaporin 4 and -1 were detected in infratentorial subependymomas in the entire tumor tissue." (PMID 26115524, 2015). "We speculate that extracellular environments of infra- and supratentorial subependymomas are different and lead to different distribution patterns of aquaporin 4 and -1." (PMID 26115524, 2015). "The reason for the different distribution pattern of aquaporin 4 in subependymomas still remains unclear." (PMID 26115524, 2015).
sudden infant death syndrome (1 paper, 2019). Unexpected death in infancy which remains unexplained following autopsy, review of the medical history, and investigation of the death circumstances and death scene. "In addition, genetic variation in AQP4, and potentially altered Kir4.1 function, are predisposing factors for sudden infant death syndrome (SIDS)." (PMID 31027200, 2019).
testicular tumour (1 paper, 2017). "The two anti-AQP-4 antibody-negative patients were a man who developed a testicular tumour and a woman who had recurrent attacks." (PMID 29568625, 2017).
Tetraparesis (1 paper, 2024). Weakness of all four limbs. "The patient had a long history of recurrent AQP4 attacks spanning 18 years, with more than 15 attacks since disease onset, and already had chronic severe tetraparesis." (PMID 38185760, 2024).
thyroid tumor (1 paper, 2012). A benign or malignant neoplasm affecting the thyroid gland. "Our study is the first report showing that AQP4 expresses in thyroid tumors; follicular cell-derived tumors, except for undifferentiated carcinoma, frequently produce AQP4." (PMID 22808259, 2012). "From this point of view, it is conceivable that the expression of AQP3 and/or AQP4 may contribute the biological behavior of thyroid tumors." (PMID 22808259, 2012). "The differential expressions of AQP3 and AQP4 may reflect the biological nature and/or function of normal, hyperplastic, and neoplastic thyroid cells and additionally may have value in determining differential diagnoses of thyroid tumors." (PMID 22808259, 2012). "In conclusion, our findings suggest that the differential expressions of AQP3 and AQP4 may reflect the biological nature and/or function of normal, hyperplastic, and neoplastic thyroid cells and, additionally, have some value for diagnosing thyroid tumors." (PMID 22808259, 2012).
Tolosa-Hunt syndrome (1 paper, 2024). "This was a rare case of AQP4-immunoglobulin G seropositivity in a patient with Tolosa-Hunt syndrome." (PMID 38419701, 2024). "Our findings may expand the clinical phenotype of NMOSD and indicate that clinicians should consider testing for AQP4 antibodies in patients with Tolosa-Hunt syndrome." (PMID 38419701, 2024).
ulcers (1 paper, 2025). "Dysregulation of AQP4 in the stomach may be linked to abnormal gastric acid secretion and the formation of ulcers." (PMID 40255569, 2025). "Dysregulation of AQP4 expression may lead to altered acid secretion and gastric mucosal damage, potentially contributing to ulcer formation." (PMID 40255569, 2025).
undifferentiated thyroid carcinoma (1 paper, 2012). "We should also consider the possibility of other AQPs in undifferentiated thyroid carcinoma in which neither AQP3 nor AQP4 was expressed." (PMID 22808259, 2012).
urinary tract infection (1 paper, 2019). "Despite better motor outcomes among patients with MOG-Ab disease, persistent bladder dysfunction (eg, urgency, hesitancy, incontinence, frequent urinary tract infections) was more common among patients with MOG-Ab disease than patients with AQP4-Ab disease (17 patients [59%] vs 21 patients [48%])." (PMID 31596489, 2019).
Varicella zoster virus infection (1 paper, 2021). "Varicella zoster virus infection-associated cases with MOG/AQP4 antibody associated central nervous system disorders." (PMID 34737756, 2021).
visual disorder (1 paper, 2023). "We found anti-aquaporin-4 antibodies in a single patient with a non-specific visual disorder." (PMID 37046492, 2023).
tumor (134 papers, 2007 to 2026). "The long-term outcomes seem to be favorable, although relapses can be seen in 20-30% of the cases with higher rates associated with concurrent NMDAR-IgG antibodies, AQP-4 antibodies, and tumor at the onset of symptoms." (PMID 41497949, 2025). "This autoimmune response is driven by pathogenic aquaporin-4 autoantibodies (AQP4-IgG), likely initiated by the tumor’s expression of AQP4 in a phenomenon of molecular mimicry." (PMID 40963604, 2025). "Studies have shown that increased AQP4 expression is closely associated with poor tumor prognosis, and the immune evasion capability is stronger in the AQP4 high-expression group compared to the low-expression group." (PMID 40788933, 2025). "AQP1 was found to boost endothelial cell migration and, in association with overexpression of AQP4 to regulate water influx and extracellular matrix interaction leading to tumor cell membrane filopodia formation, mechanisms linked to metastasis progression." (PMID 38476871, 2024). "The mutations or rearrangements of the Ret gene promote tumor formation, while the Aqp4 gene plays an essential role in brain water balance, astrocyte migration, nerve signal transmission, and neuroinflammation." (PMID 38317025, 2024). "We also found that tumor-associated macrophages tended to polarize toward M2 macrophages in the high AQP4 group." (PMID 36599974, 2023). "Male sex, age > 45 years, and presentation with nausea and vomiting have been identified as risk factors for tumor association in European AQP4-IgG-positive patients." (PMID 37022481, 2023). "The relationship between AQP4 gene levels and tumor-associated immune cell effector genes was also investigated." (PMID 36523816, 2022). "Data displayed that a sustained AQP4 expression was associated with an elevated Ki-67 index and aAQP4 marked tumor and endothelial cells in cytoplasm and plasma membranes." (PMID 36077720, 2022). "Increased expressionof AQP4 and loss of its localization in the astrocyte end-feet are associatedwith cell motility; in particular, during a pathology and tumor growth." (PMID 36348713, 2022). "We used bioinformatics analysis to investigate the immunoregulatory function of AQP4, including its correlation with immunity, anti-tumor immune processes, immunotherapy, immune infiltration, tumor mutational burden (TMB), stemness, mutation, and pan-cancer." (PMID 36523816, 2022). "Together with the increased staining intensity of AQP4 in peritumoral regions, this validates that edema causes hyperintensity on in vivo T2w images and is, thus, also included in tumor volume estimations on in vivo T2w images." (PMID 34441246, 2021). "Strikingly, GBM cells were observed to migrate along blood vessels near AQP4+ astrocytes and induce loss of AQP4 in astrocytes as the tumor grows." (PMID 33805316, 2021). "The median age of our AQP4‐positive paraneoplastic NMOSD patients is 50 years that is associated to the late age of tumor onset." (PMID 34520629, 2021). "AQP4 was also found to have significant statistical correlations to microsatellite instability, tumor mutational burden, immune cell infiltration, protein phosphorylation and clinical prognosis across multiple tumors." (PMID 34113257, 2021). "Despite the interesting implications associated with AQP4 and its significant potential as a potential therapeutic target, the mechanisms of its potential effects on tumorigenesis or tumor suppression remain elusive." (PMID 34113257, 2021). "Vessels that were at the tumor interface exhibited a precipitous loss of AQP-4 within the tumor parenchyma." (PMID 31695842, 2019). "The second hit is an event that compromises the blood-brain barrier (BBB), such as tumor-induced production of other antibodies, allowing the AQP4-IgG to enter the central nervous system and cause disease, which also explains cases where the tumor itself is AQP4-negative." (PMID 40963604, 2025). "These functions associate AQP4 with tumor-promoting functions." (PMID 41324079, 2025).
tumor (continued). "Moreover, the IDO1/TDO–Kyn–AHR–AQP4 signaling axis, together with AQP4’s interaction with tumor-associated immune components such as macrophages, warrant the exploration of combined therapeutic approaches." (PMID 41324079, 2025). "The loss of polarity in AQP4 in tumours may be connected to the loss of the protein that maintains it in place." (PMID 39247976, 2024). "Cross-reactivity with bacterial antigens that resemble AQP4 or an antibody-mediated response to AQP4 expressed by tumor cells may be the initial mechanisms underlying NMOSD." (PMID 38440735, 2024). "While the association between neoplasms and AQP4-seropositive neuromyelitis optica spectrum disorder (NMOSD) has been investigated in previous studies, data on patients affected by MOG antibody-associated disease (MOGAD) are still lacking and limited on few case reports." (PMID 37360349, 2023). "Aquaporin-4, as a water channel protein encoded by AQP4 in the brain, is reported to alter its aggregation status to affect plasma membrane dynamics and provide the potential for metastasis of tumor cells and components of the tumor microenvironment." (PMID 36599974, 2023). "The increased expression of AQP6 in the membrane may be caused by the high oxidative state of the tumor cells, similar to what was previously demonstrated for AQP4 in astrocytes." (PMID 35741021, 2022). "We then sought to determine the association between AQP4 gene expression and the degree of tumor immune cell infiltration across different cancer data available in TCGA using the TIMER, MCPCOUNTER, CIBERSORT-ABS, XCELL, CIBERSORT, QUANTISEQ and EPIC algorithms." (PMID 34113257, 2021). "The AQP4 expression in the CNS has been associated with neuroinflammatory conditions such as neuromyelitis optica spectrum disorders, tumor types and grades, tumor proliferation, migration, angiogenesis and tumor-associated edema in people." (PMID 33455577, 2021). "Data mining of co-expressed and anti-correlated genes depicted the association of AQP4 to physiological functions in normal lung tissue which may be progressively lost during tumor dedifferentiation." (PMID 21548930, 2011). "Coexistence with other neural antibodies (e.g., AQP4-IgG or NMDAR-IgG) may elevate tumor risk." (PMID 41993178, 2026). "In addition, AQP1 upregulation is associated with angiogenesis and tumor-associated edema formation and AQP4 redistribution might be functional in the reabsorption of excess cerebral fluid during vasogenic edema." (PMID 34712604, 2021). "Additionally, the enhancement of AQP4 is highly associated with tumor-related brain edema." (PMID 32182968, 2020). "First, the tumor mass produces an anatomical distortion that can lead to astrocytic displacement of AQP4 in peritumoral areas; this phenomenon is known as tumor mass effect." (PMID 41596575, 2026). "Pharmacological inhibitors, isoform-specific regulators, and novel delivery systems (e.g., nanoparticle-conjugated agents) offer avenues for disrupting AQP4-mediated tumor support." (PMID 41324079, 2025). "EVs containing AQP4 tetramers promote cell migration, while those with AQP4 orthogonal arrays of particles (OAPs) induce apoptosis, highlighting a novel mechanism by which AQP4 modulates the tumour microenvironment." (PMID 40806720, 2025). "The identification of an AQP4-expressing tumor in a patient with NMOSD is a critical finding that should be treated as a therapeutic emergency." (PMID 40963604, 2025). "Our findings differ from paraneoplastic AQP4 + NMOSD in which AQP4 expression in tumor tissue is more frequently reported." (PMID 39932929, 2025). "Histological analyses have shown that AQP4 is frequently upregulated around aberrant tumor vasculature and accumulates near dilated or disorganized perivascular spaces." (PMID 41324079, 2025).